TNF (tumor necrosis factor)
Diseases named in the same sentence as TNF in open-access papers (continued):
Sharing a sentence is not in itself a finding about the gene and the disease.
Hyperglycemia (continued). "In another study in MLDS-injected mice, treatment with troglitazone prevented hyperglycemia, suppressed insulitis and inhibited TNF-a production from intraperitoneal exudate cells." (PMID 24379032, 2013). "In fact, it is well known that SOCS3 is modulated by oxidative stress in response to hyperglycemia and the TNF-α production is induced by H2O2 via oxidative stress-related signal pathways." (PMID 23533689, 2013). "Data from other targets suggest that hyperglycemia-induced TNFα can activate SOCS3, leading to impaired insulin signaling." (PMID 23592917, 2013). "In the present study we found that hyperglycemia downregulates AR through NF-κB activation, and that this inhibitory effect is further increased by TNFα." (PMID 24058525, 2013). "In conclusion, our results suggest that hyperglycemia and TNF-α play an important role in protecting against prostate cancer by reducing androgen receptor levels via NF-κB." (PMID 24058525, 2013). "Hyperglycemia-induced TNFα levels promote insulin resistance in retinal Müller cells, noted through increased phosphorylation of IRS-1Ser307 and IRTyr960." (PMID 23592917, 2013). "Our study revealed that Kolaviron treatment abrogated hyperglycemia induced increase in the hepatic concentration of TNF-α." (PMID 24359406, 2013). "One of the key responses of Müller cells to hyperglycemia is an increase in cytokines, specifically IL-1β and TNFα." (PMID 23592917, 2013). "In conclusion, our results suggest that hyperglycemia and TNF-α play an important role in protecting type 2 diabetic patients against PCa by reducing AR levels via NF-κB activation." (PMID 24058525, 2013). "Inhibition of molecules downstream of TNFα and involved in ROS production and hyperglycaemia, as well as specific activation of NFκB cascades, all had an improving or attenuated outcome on AKI prevention." (PMID 24172336, 2013). "TNF-α and hyperglycemia have been shown to induce plasminogen activator inhibitor-1 (PAI-1) and cell adhesion molecules (VCAM-1 and ICAM-1) expression in human vascular endothelial cells." (PMID 23785355, 2013). "In the present study we provide first evidence that hyperglycemia downregulates AR through NF-κB activation, and that this inhibitory effect is further increased by TNFα." (PMID 24058525, 2013). ">A pathogenic role for tumor necrosis factor-alpha (TNF-α) in mice with Type 1- and 2- diabetes and the efficacy of anti- TNF-α treatment in ameliorating hyperglycemia and restoring normal insulin has been recently addressed." (PMID 22867128, 2012). "Circulating levels of TNF-α, IL-6 and nitrotyrosine were consistently and time-dependently elevated after postchallenge hyperglycemia." (PMID 22397368, 2012). "Hyperglycemia spike had been shown to acutely increase the levels of circulating proinflammatory cytokines, including tumor necrosis factor-alpha (TNF-α) and interleukin-6 (IL-6), in subjects with IGT and these responses are attenuated by antioxidant." (PMID 22397368, 2012). "We have recently shown that hyperglycemia induces proinflammatory cytokine release (IL-1, IL-6, and TNF-α) in monocytes via an NF-κB-dependent pathway." (PMID 23320034, 2012). "According to the authors, these observations suggest that the tissues of women with GDM increase the release of TNF-α in response to hyperglycemia." (PMID 22462002, 2012). "The major findings in this study were as follows: firstly, postchallenge hyperglycemia can rapidly elicit circulating TNF-α, IL-6 and nitrotyrosine levels after 75 g-OGTT in all patients regardless of glucose tolerance status or the presence or absence of CAD." (PMID 22397368, 2012). "Many factors are known to activate NF-κB, including inflammatory cytokines such as tumor necrosis factor alpha (TNFα) and interleukin (IL)-1, carcinogens (cigarette smoke), UV radiation, hyperglycemia and tumor promoters." (PMID 22710558, 2012). "Hyperglycemia increases the inflammatory markers' tumor necrosis factor (TNF)-α, interleukin (IL)-1, and IL-6." (PMID 21716679, 2011).
Hyperglycemia (continued). "In summary, our study shows that controlling post-meal hyperglycaemia with prandial + basal insulin attenuates the meal-induced increases in hsCRP, TNF-α and interleukin-6 compared with basal insulin once daily, both plus metformin." (PMID 21517955, 2011). "Experimental studies have shown that hyperglycemia stimulates the release of the inflammatory cytokines tumor necrosis factor-alpha (TNF-α) and interleukin-6 (IL-6) from various cells such as monocytes." (PMID 21663637, 2011). "Hyperglycemia-induced ROS stimulates signal transduction to instigate inflammatory cytokines, e.g. TNF-α, IFN-γ and TGF-β." (PMID 21118576, 2010). "Ectopic expression of hTERT has also been shown to increase radioresistance of adult human mesenchymal stem cells, to circumvent hyperglycemia-induced premature senescence, and to prevent apoptosis induced by tumor necrosis factor." (PMID 19272180, 2009). "Hyperglycemia enhances plasma levels of interleukin (IL)-6 and tumor necrosis factor-alpha (TNF-α) in normal healthy volunteers." (PMID 18710523, 2008). "After endotoxin stimulation, the induction of hyperglycemia led to a slight but significant increase in IL-6 in healthy volunteers, whereas TNF-α levels were unaffected." (PMID 18710523, 2008). "The induction of acute hyperglycaemia in healthy humans elevated circulating levels of TNF-α and IL-6, although these elevations were very modest, especially when compared with cytokine increases observed during inflammatory reactions." (PMID 18290856, 2008). "In a porcine model, stress hyperglycemia led to a significantly enhanced inflammation as shown by elevated TNF-α and IL-6 levels." (PMID 18710523, 2008). "Hyperglycemia has been shown to increase the release of pro-inflammatory mediators such as IL-6, IL-8, and TNF, which are important in inflammation." (PMID 16999863, 2006). "Hyperglycemia also increases the release of proinflammatory cytokines, such as interleukin 1β (IL-1β), IL-6, IL-18, tumor necrosis factor alpha (TNF-α), and transforming growth factor β1 (TGF-β1), which favor cardiac myocyte apoptosis and the development of diabetic cardiomyopathy." (PMID 41010907, 2025). "Pro-inflammatory immune cells and their cytokines, such as TNF-α and IL-6, impair adipose function and induce systemic insulin resistance; secondary hyperglycemia and metabolic disturbances, such as AGEs accumulation, then exacerbate periodontal immuno-stress and destruction." (PMID 41246338, 2025). "Maternal diabetes is associated with a range of inflammatory and metabolic disturbances, including hyperinsulinemia, hyperglycemia, and elevated levels of cholesterol, ketones, amino acids, free radicals, and inflammatory markers such as tumor necrosis factor-alpha, cytokines, and interleukins." (PMID 39873760, 2025). "Thus, hyperglycemia stimulates macrophages to produce proinflammatory factors macrophages (TNF-alpha, IL1-beta, S100A9, S10012), elevates expression of TLRs, and drives epigenetic changes supporting hyperglycemic memory related to vascular complications." (PMID 40004134, 2025). "Chronic and inadequately treated hyperglycemia in patients diagnosed with DM can activate inflammatory responses through citokine production (TNF-α, NFkB, IL-1, IL-6, etc.)from various types of cells (such as macrophages, lymphocytes, granulocytes, fibroblasts, mast and endothelial cells)." (PMID 40299501, 2025). "The present findings showed that hyperglycemia promoted the pro-inflammatory phenotype in macrophages, which was characterized by increased expressions of marker pro-inflammatory mediators, including TNF-α, IL-6, IL-1β, and iNOS." (PMID 40001441, 2025). "Hyperglycemia triggers immune cells to release inflammatory mediators (including TNF-α, IL-1β, IL-6, NF-κB, TGF-β, and adhesion molecules), which further contribute to β-cell dysfunction, insulin resistance, and progression of complications such as vascular damage, neuropathy, and CVD cell loss." (PMID 40299501, 2025).
Hyperglycemia (continued). "Hyperglycemia can activate retinal glial cells and microglia, leading to the production of inflammatory cytokines such as monocyte chemotactic protein-1, vascular endothelial growth factor, TNF-α, and IL-6." (PMID 40469434, 2025). "Hyperglycemia exacerbates oxidative stress through the production of reactive oxygen species (ROS) and inflammatory mediators such as interleukin (IL)-1β, IL-23, and tumor necrosis factor (TNF)-α, which disrupt the bone healing process." (PMID 40870403, 2025). "Extended hyperglycemia augmented TNF‐α secretion from adipocytes." (PMID 40746010, 2025). "Met therapeutic effects in lowering hyperglycemia in obese people, those with T2DM, or those with impaired glucose tolerance may be mostly linked to decreased TNF-α and CX3CL1 production." (PMID 40088335, 2025). "While full GR agonists enable suppression of pro-inflammatory immune responses (e.g., TNF-α expression), they may also result in unwanted adverse effects such as hyperglycemia, skin atrophy, or bone resorption." (PMID 39817774, 2025). "For instance, hyperglycemia-induced advanced glycation end products (AGEs) may interfere with vitamin K’s ability to inhibit pro-inflammatory cytokines like TNF-α." (PMID 40686819, 2025). "However, hyperglycemia further promotes pro-inflammatory and profibrotic responses, leading to the upregulation of tumor necrosis factor-α (TNF-α) and transforming growth factor-β (TGF-β)." (PMID 40002316, 2025). "Hyperglycemia also elevates TNF-α production in glial cells, particularly microglia." (PMID 41008312, 2025). "Hyperglycemia-driven ROS accumulation promotes the overexpression of pro-inflammatory cytokines (e.g., TNF-α, IL-1β), matrix metalloproteinases (MMPs), and suppression of tissue inhibitors of metalloproteinases (TIMPs), ultimately resulting in extracellular matrix degradation." (PMID 40728954, 2025). "Hyperglycemia induces an imbalance in the polarization of macrophages and leads to increases in inflammatory cytokines such as interleukin-1β (IL-1β), IL-6 and tumor necrosis factor alpha (TNF-α), preventing the transition from M1 to M2 macrophages." (PMID 39015252, 2024). "Hyperglycemia in DM leads to the glycation of various proteins, triggering an inflammatory milieu at the cellular and tissue levels, with increased cytokines levels such as tumour necrosis factor-alpha (TNF-α), interleukin-6, and C-reactive protein." (PMID 39553031, 2024). "Experimental validation proved that mSMG ameliorated hyperglycemia, IR, and TNF-α, enhanced glucose consumption and glycogen synthesis, relieved the phosphorylation of JNK1 and IRS-2 (Ser388), and elevated the phosphorylation of Akt (Ser473) and GSK-3β (Ser9) and GLUT2 expression in KK-Ay mice." (PMID 39285464, 2024). "Existing hyperglycaemia during GDM, due to insulin insufficiency, is known to cause certain immune dysfunction that leads to leukocyte dysfunction and the increased production and secretion of cytokines, like IL-1β, IL-6 and TNF-α." (PMID 39518962, 2024). "Furthermore, chronic exposure to hyperglycemia can produce inflammatory factors such as tumor necrosis factor-alpha (TNF-α) and interleukin-6 (IL-6)." (PMID 38778429, 2024). "Subsequent experimental verification proved that mSMG could ameliorate hyperglycemia, IR, and serum and liver TNF-α." (PMID 39285464, 2024). "Hyperglycemia also plays a direct role in macrophage polarization towards the M1 phenotype through the formation of advanced glycation end products that contribute to greater expression and production of pro-inflammatory cytokines (e.g., TNF-α)." (PMID 39408569, 2024). "There is increasing evidence that cytokines (such as TNF-α, IFN-γ), mutations in myelin protein zero (MPZ), Acanthamoeba and long-term hyperglycemia conditions induce Schwann cell death, then disrupt peripheral nerve support and neuropathy, and delay peripheral nerve regeneration." (PMID 38388913, 2024).
Hyperglycemia (continued). "Secondly, hyperglycemia promotes the chronic release of inflammatory mediators such as tumor necrosis factor-alpha (TNF-α) and interleukin-6 (IL-6), creating a pro-inflammatory environment that leads to the accumulation of collagen and extracellular matrix, ultimately resulting in fibrosis." (PMID 39407755, 2024). "Hyperglycemia and oxidative stress induce NF-κB activation, which translocates to the nucleus and initiates the transcription of pro-inflammatory and pro-fibrotic genes such as TNF-α, IL-6, and MCP-1." (PMID 39795078, 2024). "In our systematic review, it was mentioned that probiotics could prevent hyperglycemia by reducing the levels of IL-6 and TNF-α, thereby improving insulin sensitivity." (PMID 38529045, 2024). "To this end we examined whether CysLTR1 is necessary for montelukast in alleviating inflammation under the influence of hyperglycemia and TNF-α." (PMID 39504050, 2024). "In addition, hyperglycemia promoted the release of proinflammatory factors such as tumor necrosis factor-α(TNF-α) and interleukin-6 (IL-6) in vitro." (PMID 37008926, 2023). "Notably, perioperative hyperglycemia was shown to attenuate postoperative immune activation with a significant suppression of serum TNF-α release in cancer patients of esophageal or pancreatic resections." (PMID 36765695, 2023). "In addition, stress-induced hyperglycemia can also trigger an inflammatory response, such as increasing the production of inflammatory cytokines (such as TNF-α, IL-1β, and IL-6), which further exacerbate lung tissue inflammation." (PMID 37658378, 2023). "Collectively, the limited data show that the glucose fluctuation and hyperglycemia may affect the TNF-α expression and subsequent cancer progression, which should be clarified through further investigations." (PMID 36765695, 2023). "Interestingly, we observed a significant difference only in TNF-α and the ratios of oxLDL with lipoproteins, with higher levels in hypertension and hyperglycemia, and an increase along with the number of MS components." (PMID 37529617, 2023). "Therefore, this study suggests that SME significantly affects the expression of TNF-α through the inhibition of NF-κB activation in nPQ cells in the liver tissue of hyperglycemia rats." (PMID 38001866, 2023). "Furthermore, hyperglycemia promotes the release of tumor necrosis factor-alpha (TNF-α), a well-known contributor to IR, from mononuclear cells." (PMID 37762427, 2023). "Moreover, hyperglycemia induces the production of numerous inflammatory factors, such as IL-6 and TNF-α, that can induce epithelial mesenchymal transition, thereby promoting tumor cell invasion and inhibiting apoptosis." (PMID 38152132, 2023). "In addition, hyperglycemia can stimulate monocytes and macrophages to increase IL⁃6 secretion by inducing TNF⁃α secretion, thus promoting tumor progression and infiltration." (PMID 36672448, 2023). "Hyperglycemia also triggers the release of proinflammatory cytokines, including interleukin-1β (IL-1β), IL-6, IL-18, tumor necrosis factor-α (TNF-α) and transforming growth factor-β (1 TGF-β1), which leads to cardiomyocyte apoptosis, promoting the occurrence of diabetic cardiomyopathy." (PMID 37479697, 2023). "In response to different stimuli such as TNF-α, bacterial lipopolysaccharide (LPS), hyperglycemia, shear stress, oxidative stress, and hypoxia/reperfusion, IκB is degraded, and NF-κB rapidly activates and translocates into the nucleus to initiate the transcription of immune and inflammatory genes." (PMID 37049512, 2023). "Maternal hyperglycemia leads to excessive production of proinflammatory cytokines in the placenta and directly affects the fetus, and neonatal hyperglycemia also promotes the production of interleukin 1β (IL-1β), tumor necrosis factor α (TNF-α) and toll-like receptor activity in spleen cells." (PMID 37735200, 2023).
Hyperglycemia (continued). "Interestingly, both TNF-α and IL-6 have been shown to increase similarly during experimental hyperglycemia along with rises in IL-18 and FGF-21 and suppression of VEGF." (PMID 37400734, 2023). "In fact, it has been reported that pro-inflammatory cytokines (e.g., TNFα, interleukin 1β (IL-1β), interleukin 18 (IL-18) and IL-6) are increased in acute hyperglycemia, whereas in the opposite condition, when insulin is working, these cytokines are significantly decreased." (PMID 38137918, 2023). "In general, hyperglycemia, ROS, and TNF-α are portent activators of SREBP1." (PMID 36677854, 2023). "Due to postprandial hyperglycemia and hyperlipidemia, there is an increase in circulating pro-inflammatory cytokines (IL-1β, TNFα and IL-6) in the blood, which originate from adipose tissue and connective tissue cells and promote chronic low-grade inflammation." (PMID 38137918, 2023). "Hyperglycemia stimulates a hyper-activation of microglia with the consequent development of the inflammatory process mediated by interleukin (IL)-1β, tumor necrosis factor (TNF)-α, IL-6, and vascular endothelial growth factor (VEGF)." (PMID 35956066, 2022). "Exposure of INS-1E cells to high glucose concentration to mimic chronic hyperglycemia (30 mM glucose for 48 h) or pro-inflammatory conditions (cytomix: 10 U/ml IL-1β, 500 U/ml TNF-α, and 100 U/ml IFN-γ for 24 h) led to a ~2-3 fold increase in REV-ERBα protein expression (P < 0.05 and P < 0.001)." (PMID 35428762, 2022). "It has been reported that hyperglycemia increases advanced glycationend product formation and reactive oxygen species (ROS) and activates NF-κB, followed by an increase in cytokines (IL-1, IL-6, TNF-α)." (PMID 36406423, 2022). "However, hyperglycemia significantly enhanced TNFα release 6 h after stimulation with Hb-Hp2-2 complexes (1 μg/mL: 1.65 times, p-value < 0.01; 10 μg/mL: 1.61 times, p-value < 0.01)." (PMID 35163309, 2022). "Moreover, in mice, tumor necrosis factor-α (TNF-α) and insulin-like growth factor 1 (IGF1) promote the expression of glucose transporter protein type 1 (GLUT-1), causing hyperglycemia in the placenta, which accelerates the overgrowth of the fetus." (PMID 35267914, 2022). "TFP5 treatment decreased hyperglycemia-induced IL-6, IL-1β, and TNF-α upregulation." (PMID 35874807, 2022). "The occurrence of stress hyperglycemia involves activation of the hypothalamic-pituitary axis and sympatho-adrenal system and increases the release of epinephrine, norepinephrine, and pro-inflammatory cytokines (TNF-α, IL-1, and IL-6)." (PMID 35645975, 2022). "Hyperglycemia activates NFκB which will trigger the expression of various adhesion molecules, chemokines and cytokines, including tumor necrosis factor-alpha (TNF-α), interleukin, transcription growth factor-beta (TGF-β), Bcl2 and other proinflammatory proteins." (PMID 35027069, 2022). "Our experimental model of hyperglycemia resulted in a visible alteration of the HuASCs immunomodulatory properties and triggered an augmentation of the pro-inflammatory marker expression, including IL-1β and TNF-α at both the mRNA and the proteins levels." (PMID 35327652, 2022). "Several studies have shown that curcumin improves insulin sensitivity, decreases hyperglycemia, improves insulin levels, reduces proinflammatory mediators such as interleukin (IL-6, IL-1β) and tumor necrosis factor-α (TNF-α) in diabetic patients, and increases their global antioxidant power." (PMID 36297570, 2022). "The pro-inflammatory environment resulting from hyperglycemia and/or insulin resistance is the result of the higher expression of inflammatory mediators, such as IL-1β, IL-6, TNF-α, TGF-β, IKKβ, and JNK, that may have local or systemic action." (PMID 36552014, 2022).